CCR4 (C-C motif chemokine receptor 4)
Diseases named in the same sentence as CCR4 in open-access papers (continued):
Sharing a sentence is not in itself a finding about the gene and the disease.
tumor (continued). "CCL2 has been reported to bind its receptors CCR2 and CCR4 on lymphocytes, resulting in recruiting immune cells to tumor sites, which causes immunosuppression." (PMID 31207928, 2019). "Given the large proportion of Tregs within the CD4+ population in tumor lesions, it is tempting to associate the presence of CCR4+ effector cells to Tregs." (PMID 30420855, 2018). "CCL2 secreted by GBM cells binds to its receptor on CCR4+ cells to cause them to migrate to the tumor microenvironment and surround the GBM (Ti-CCR4 cells)." (PMID 29312296, 2017). "CCR4 is a marker for effector Treg cells in humans, and depletion of CCR4+ Treg cells in vitro causes the enhancement of anti-tumor immunity." (PMID 27250643, 2016). "CCL22 on tumors recruits CCR4+ Treg cells to the site and has been associated with tumor progression through their suppression of effector T cells that target tumor antigens." (PMID 26834735, 2015). "In the first experiment, where the two different isotypes (huIgG1 and muIgG2a) of anti-CCR4 9E10J antibody were compared, the highest anti-tumor activity was observed for the chimeric antibody variant comprising the murine IgG2a Fc portion." (PMID 25080123, 2014). "CCL22, secreted by the tumor cells causes accumulation of CCR4+ T-regulatory cells at tumor site resulting in immune suppression." (PMID 24384839, 2013). "Human CCR4+ tumor-bearing mice treated once with intravenous infusion of AAV8 virions encoding the h1567 (AAV8-h1567) minibody showed anti-tumor activity in vivo and increased survival." (PMID 22973452, 2012). "While expression of CCR4 by tumor cells is associated with their skin involvement, CCR4 also has an important role in normal and tumor immunity." (PMID 22973452, 2012). "Together, these data suggest a selective exclusion of CXCR3+ conventional T cells from the tumor-associated mucosa, with a concomitant recruitment of CCR4+ Treg and conventional CD4+ T cells." (PMID 22319577, 2012). "It has been demonstrated that chemokine receptor CCR4 is selectively expressed by TReg cells, and the CCR4 and CCR4-associate chemokines axis is one of the most described tumor TReg recruitment axes." (PMID 22481922, 2012). "In addition, blocking specific chemokine and cytokine receptors such as CCR2, CCR4 or Il-6R can reduce the recruitment of tumor-associated macrophages (TAMs), myeloid-derived suppressor cells (MDSCs) or regulatory T cells (Tregs)." (PMID 38928238, 2024). "Moreover, the limited availability of tumor tissue samples precluded further investigation into the association between CCL22 and CCR4 expression and tumor metastasis." (PMID 39513112, 2024). "Mogamulizumab conveys antibody‐dependent cell‐mediated cytotoxicity to CCR4‐expressing malignant T cells, but tumor evasion with loss of CCR4 may cause drug resistance." (PMID 37144705, 2023). "Loss of CCR4 expression by tumor T cells can appear after mogamulizumab therapy." (PMID 36765704, 2023). "CXCR4 and CCR4 are attractive candidates for cancer studies since they have been reported to modulate physiological processes associated with proliferation, survival, tumor growth, invasions, and epidermal growth factor receptors." (PMID 37489388, 2023). "The pro-tumorous role of CCR4 in the progression of T-cell-associated lymphoma is well known and explained by a higher infiltration with tumor-promoting T-cell subpopulations, such as regulatory T cells (Tregs) and TH2 cells, which both show an increased expression of CCR4." (PMID 37371612, 2023). "For example, studies have suggested that CCR4 is significantly associated with the tumor microenvironment (TME) and prognosis in HNSCC, and that CCR4 may serve as a new potential molecular target for HNSCC therapy." (PMID 36671475, 2022). "CCL22 has been implicated in the recruitment of CCR4+ Tregs from peripheral blood to tumor tissues." (PMID 33710805, 2021).
tumor (continued). "Indeed, CCR4 is expressed by Treg cells whose accumulation in the tumor microenvironment is a cause of resistance to immune therapy." (PMID 33669094, 2021). "Additionally, Th2 and a small population of Th17 cells also express CCR4; however, recruitment of these cells to tumor sites is associated with a poor prognosis." (PMID 33628584, 2021). "However, since CCR4 is expressed on Treg cells as well as ATLL tumor cells, there are concerns regarding an increased risk of severe acute GVHD in ATLL patients treated with pretransplant mogamulizumab." (PMID 32006150, 2020). "CCR4 is associated with high tumor recurrence and poor prognosis of gastric cancer patients." (PMID 28415693, 2017). "Tumor targeting with a human mAb directed against tumor-associated markers, such as CCR4, might provide a powerful therapeutic strategy against CTCL." (PMID 22973452, 2012). "The tumor -associated CCR4 may contribute to the metastatic spread of these tumor cells." (PMID 28415693, 2017). "The anti-ICOSL neutralizing antibodies induced apoptosis and suppressed CCR4 expression on tumor cells, inhibiting CCR4-CCL17-mediated migration." (PMID 41683829, 2026). "HRS cells secrete the chemokines CCL17 (also known as thymus and activation-regulated chemokine, TARC) and CCL22, which recruit CCR4-expressing Th2 cells and Tregs, promoting an immunosuppressive milieu that facilitates tumor survival." (PMID 40806636, 2025). "In tumor-stage MF, CCR4 is often co-expressed with CD30 on large atypical tumor cells infiltrating the dermis." (PMID 40861461, 2025). "CCR4, CMA1, ADCY1, RDH12, and ENTPD2 exhibited higher expression levels in the low-risk group, indicating their possible tumor-suppressive functions." (PMID 40243888, 2025). "The TGF‐βpathway genes (THBS1 and SMAD2) report on epithelial–mesenchymal transition and immunosuppressive signaling, while Th2‐associated markers (CCR4, GATA3) indicate a helper T‐cell polarization state that favors tumor progression." (PMID 41407509, 2025). "In GBM, tumor-derived chemokines such as CCL2 and CCL22 bind to CCR4 on Tregs and have been implicated in their selective recruitment to the tumor." (PMID 40867165, 2025). "The tumor-promoting effects of M2-like macrophages-derived CCL17 on the malignant behaviors of ECSS was depended on the activation of CCR4/ERK/PD-L1 pathway." (PMID 39473097, 2025). "CCR4 antagonists markedly reduce tumor-infiltrating Treg numbers and enhance responsiveness to sorafenib in murine liver cancer models." (PMID 40607438, 2025). "M1 macrophage-derived EVs similarly induce tumor death by decreasing the expression levels of CCR4, Foxp3, and CTLA-4 in canine peripheral mononuclear cells cocultured with tumor cells." (PMID 40530018, 2025). "Tumor cells and tumor-associated macrophages upregulate CCL22 and CCL17, ligands for CCR4, which promote Treg chemotaxis toward the tumor microenvironment." (PMID 41394821, 2025). "Concurrently, integration of chemokine receptors such as CXCR2 or CCR4 enhances CAR-γδT responsiveness to tumor-derived chemokines, improving tumor infiltration and local efficacy." (PMID 41488642, 2025). "utilized a more sensitive CCR4 detection kit, revealing CCR4 expression across all stages of MF, with higher levels in tumor-stage lesions." (PMID 40861461, 2025). "Instead, it recruited a large number of CD4T_FOXP3+ regulatory T cells by highly expressing CCL5 and binding to the tumor chemokine CCR4 axis, forming a dense immunosuppressive “chemical barrier”." (PMID 40948762, 2025). "CCL22 is a chemokine that recruits CCR4-expressing cells, particularly Treg, to sites of inflammation or immune regulation, such as tumor microenvironments." (PMID 40894040, 2025). "The tumor-promoting effects of M2-like macrophages-derived CCL17 on ECSS was depended on the activation of CCR4/ERK/PD-L1 pathway." (PMID 39473097, 2025).
tumor (continued). "A further advantage of targeting CCR4 is the depletion of immunosuppressive Th2 cells and Tregs, enabling reactivation of endogenous anti-tumor responses that can act synergistically to improve outcomes." (PMID 41295262, 2025). "In a pancreatic-cancer model, pharmacological CCR4 antagonism lowers Treg density and slows tumour growth." (PMID 41291326, 2025). "Therapeutic approaches aimed at disrupting this immunoregulatory axis—such as the monoclonal anti-CCR4 antibody mogamulizumab and small-molecule CCR4 antagonists including FLX475 and CCR4-351—have shown promise in restoring anti-tumor immunity." (PMID 40806636, 2025). "CCR4 is also widely expressed on tumor cells in adult T-cell leukemia/lymphoma and other peripheral T-cell lymphomas." (PMID 40861461, 2025). "In a previous study, we showed in a syngeneic in vivo model using PDA6606 cells in C57BL/6 mice that pharmacological or steric inhibition with blocking antibodies targeting CCR4 significantly increased the survival of tumor-bearing mice." (PMID 40282185, 2025). "Significant tumor control was also achieved in ATLL murine xenografts treated with CCR4 CAR-T cells." (PMID 41295262, 2025). "CCL22, produced mainly by tumor cells (or macrophage‐mediated), interacts with the receptor CCR4 on the surface of Treg cells to increase their number in the TME." (PMID 40969301, 2025). "Monoclonal antibodies like mogamulizumab effectively bind to CCR4, reducing tumour burden and enhancing patient outcomes by inhibiting the receptor’s interaction with ligands, thereby hindering malignant T-cell migration and survival." (PMID 38804300, 2024). "Addition of MDMs to 22Rv1 tumor-T cell co-cultures resulted in a decrease in CCR4 (C-C motif chemokine receptor 4) expression (Co-22 vs. Tri-22, 0.0056 vs. 0.0039, p = 0.0342) with a similar trend observed in LNCaP tri-cultures." (PMID 39414902, 2024). "In the current literature, the blockade of either CCL2 or CCR4 was reported to have additional anti-tumor influence by targeting different than Treg subsets of pro-tumorigenic cells in various cancers." (PMID 39046599, 2024). "The expression of DNMT3A increased significantly when EZH2 was knocked down; CCL22 and CCR4 were downregulated in tumor tissues, and EMT-related protein expression also changed consistent with in vitro results." (PMID 39513112, 2024). "This investigation aims to delineate the roles of CCL17 and CCR4 in modulating the tumor’s immune landscape, assessing their potential as therapeutic interventions and prognostic markers in HCC." (PMID 38914802, 2024). "Next, we further explored the relationship between CCL17, CCR4, and tumor angiogenesis in human HCC tissues." (PMID 38914802, 2024). "This property has been applied in tumour therapy by targeting CCR4, the ligand of CCL17 to reduce Treg suppression." (PMID 39031979, 2024). "Blocking this CCL22/CCR4 axis and consequently removing Treg cells leads to anti-tumor immune responses." (PMID 38318526, 2024). "Mogamulizumab, a glyco-engineered anti-CCR4 antibody, targets CCR4 and induces an antibody-dependent cellular cytotoxicity reaction leading to tumor cell death and lysis." (PMID 38824603, 2024). "CCL17 has been shown to specifically attract CCR4+ Tregs, and blocking Treg migration with a CCR4 antagonist has the potential in promoting anti‐tumour immunity." (PMID 39031979, 2024). "CCL2 is highly expressed in a variety of malignant tumor cells, but its receptors (CCR2b and CCR4) are only slightly expressed on the surface of activated CAR-T cells that target tumor antigens." (PMID 39023820, 2024). "Mogamulizumab is used in the treatment of cutaneous T-cell lymphomas (CTCLs) and works by binding to CCR4, reducing tumor burden by inhibiting Treg migration and survival." (PMID 39273290, 2024). "CCR4+Treg cells modify the environment, allowing tumor cells to escape from the immune host response." (PMID 39273632, 2024).
tumor (continued). "Overexpression of FOXP3 increases the infiltration of CCR4+Tregs cells, leading to reduced anti-tumor immune response and tumor progression." (PMID 38919615, 2024). "CCR4 is a chemokine receptor for the metastatic process of Tregs and in tumor-infiltrating Foxp3+ Treg populations, most of which express CCR4." (PMID 39329710, 2024). "Recent findings implicate the chemokine ligand 17 (CCL17) and its receptor CCR4 as pivotal players in the tumor microenvironment (TME) of various cancers." (PMID 38914802, 2024). "CCR4 expression was determined by immunohistochemistry and was classified according to the proportion of stained tumor cells (at least 10%)." (PMID 38824603, 2024). "Further validation using out-ward PCR and Sanger sequencing confirmed the presence of these three CCR4 eccDNAs in tumor samples." (PMID 39267784, 2024). "CCR4 is a therapeutic target for different malignancies due to its role in immune cell recruitment in the tumour microenvironment." (PMID 38804300, 2024). "This positions CCR4 antagonism as a potentially more versatile strategy for anti-tumor immunotherapy." (PMID 39227959, 2024). "Suppression of CCR4 due to mogamulizumab, a monoclonal antibody IgG1-k, reduces the tumor burden and enhances antitumoral activity by decreasing CCR4+Treg cells and increasing the immune response." (PMID 39273632, 2024). "In BC lymphocyte recruitment, CCL17/CCL22 acts as a ligand for CCR4, and CCL17/CCL22 is closely associated with Foxp3+ tumor-infiltrating regulatory T cells (Ti-Tregs)." (PMID 39329710, 2024). "Intriguingly, CCL17 and CCR4 were also found to be widely expressed in tumor stroma, hinting at a subtype of stromal cells, mainly immune cells, expressing these two molecules." (PMID 38914802, 2024). "CCR4 small molecule inhibitors block the migration of Treg cells and therefore keep Treg cells from entering the tumor microenvironment." (PMID 38318526, 2024). "In contrast, our findings revealed its expression in both tumor and stroma cells, as well as its receptor CCR4." (PMID 38914802, 2024). "CCR4 is highly expressed on tumor-infiltrating Tregs, contributing to their migration and accumulation in the tumor microenvironment." (PMID 39273290, 2024). "In the WM35 melanoma cell line, the CCL2 secreted by tumor cells recruited cytotoxic T lymphocytes by binding to CCR4." (PMID 38928238, 2024). "The blockade of CCR4 demonstrated a synergistic anti-tumor effect in conjunction with these immunomodulatory agents." (PMID 39227959, 2024). "Previous studies have indeed reported that intravenously administering CCR4-expressing CAR-T cells to mice with human Hodgkin lymphoma results in enhanced tumour homing and increased anticancer activity." (PMID 39596267, 2024). "As lactic acid levels increase in the TME, tumor-associated macrophages differentiate into M2 subtypes, while activated macrophages promote tumor invasion through the CCL17/CCR-4/Mtorc1 signaling axis." (PMID 37781694, 2023). "ESCC TAM-released CCL22 promoted tumor invasion and reduced patient survival via activation of the CCR4/DGKα/FAK complex in ESCC cells, revealing opportunities for targeting the tumor-promoting microenvironment to achieve anticancer effects." (PMID 37198402, 2023). "This particular type of macrophage recruits Tregs through the CC motif chemokine ligand 22–C-C motif chemokine receptor 4 (CCL22–CCR4) axis to induce immune tolerance, leading to tumor growth and metastasis." (PMID 37753074, 2023). "The number of tumor-infiltrating CD4+ T cells decreased significantly (CCR4−/−: 488 ± 72 CD4+ cells per 1 × 105 tumor cells vs. WT: 1538 ± 355 CD4+ cells per 1 × 105 tumor cells; n = 9, p = 0.0074) with a mean absolute reduction of 1050 ± 343 (72.5%)." (PMID 37371612, 2023). "CCR4 knockout had a significant effect on tumor immune cell infiltration (CCR4−/−: 9341 ± 1777 CD45+ cells per 1 × 105 tumor cells vs. WT: 17,860 ± 2462 CD45+ cells per 1 × 105 tumor cells; n = 9, p = 0.0127)." (PMID 37371612, 2023).
tumor (continued). "In the third group (tumor-bearing mice receiving therapeutic pharmacological CCR4), CCR4 inhibition started 14 days after tumor implantation." (PMID 37371612, 2023). "The expression of CCR4 in macrophages has been known for a long time, and our data indicate its importance in tumor progression." (PMID 37371612, 2023). "In our screen, we found two chemokine receptors to very specifically direct T cells into tumor-draining lymph nodes: CCR4 and CCR7." (PMID 37301772, 2023). "In the second group (prophylactic pharmacological CCR4 inhibition before tumor implantation), antagonization of CCR4 significantly decelerated tumor growth (106.0 ± 20.5 mm3) compared to the vehicle control group (129.8 ± 35.1 mm3) (p = 0.317) after 3 weeks." (PMID 37371612, 2023). "The number of CD8+ T cells decreased significantly as well (CCR4−/−: 1039 ± 263 CD8+ cells per 1 × 105 tumor cells vs. WT: 2322 ± 307 CD8+ cells per 1 × 105 tumor cells; n = 9, p = 0.0059), with a mean absolute reduction of 1283 ± 405 (59.7%)." (PMID 37371612, 2023). "In the draining lymph node, CCR7 transduced T cells were more abundant on day 4 but then slowly decreased over time, whereas CCR4 transduced T cells peaked at day 8, both in lymph node and tumor." (PMID 37301772, 2023). "The chemokine receptor 4 (CCR4) is highly expressed in various tumors and plays an important role in tumor pathogenesis." (PMID 37259456, 2023). "After five weeks, the mean tumor size was also significantly smaller in CCR4−/− mice (114.0 ± 19.2 mm3 (n = 11)) than in wildtype mice (442.1 ± 57.8 mm3 (n = 11)) (p < 0.001)." (PMID 37371612, 2023). "Especially CCR4 expression in the tumor is correlated with failure of immunotherapies and a target for therapeutic intervention, e.g., by agonists, antibody therapy or chimeric antigen receptors (CAR-) T cell immunotherapy." (PMID 36834542, 2023). "These cells have increased expression of PD-1, GITR, CTLA-4 and CCR4 in addition to other cell surface markers which inhibit anti-tumor responses." (PMID 37122749, 2023). "For instance, data from the “Protein Atlas” offer a lower survival in the later stages of PC, when tumor cells express high levels of CCR4." (PMID 37371612, 2023). "After three weeks, the mean tumor volume in CCR4-knockout mice (73.2 ± 11.6 mm3 (n = 15) was significantly lower than in wildtype mice (204.2 ± 19.1 mm3 (n = 13)) (p < 0.001)." (PMID 37371612, 2023). "In order to make it clear that CCL22 was involved in Treg infiltration during treatment, we analysis the CCR4 level in tumor infiltrated Treg, a relatively high CCR4 level was observed in Treg, we conducted a compensation experiment." (PMID 36969873, 2023). "Tumor cells and tumor-associated macrophages secrete the chemokines CCL22 and CCL17, which attract CCR4+ Treg cells." (PMID 37107673, 2023). "The accumulation of CAR-T cells in tumor tissues can be promoted by the overexpression of CCRs from T cells (e.g., CCR2b and C-C motif chemokine receptor 4) or by the overexpression of chemokines from tumor cells (e.g., RANTES and IL-15)." (PMID 36979400, 2023). "In the CCR4 prophylaxis experiment, the percentage of F4/80+ area in the control group was 6.31 ± 1.07% on day 42 after tumor implantation, while in the prophylaxis group this percentage was 2.69 ± 0.26% (p = 0.031)." (PMID 37371612, 2023). "CCR4 is a chemokine that is overexpressed by type 2 helper T cells in Tregs and certain tumor lymphocytes, such as cutaneous T-cell lymphoma tumor cells." (PMID 36765704, 2023). "Treg cells express CC chemokine receptor 4 (CCR4), the receptors of CC chemokine ligand 22 (CCL22), and can migrate to CCL22 derived from tumor cells and tumor associated macrophages in the TME, thus realizing the recruitment of Treg cells." (PMID 36908706, 2023). "CCR4 is predominantly expressed in tumor resident Tregs, enabling tumor immune evasion, and is thus regarded as a potential candidate target for cancer immunotherapy." (PMID 38283365, 2023).